CTXND1 (cortexin domain containing 1)
Synonyms: LINC01314
Gene: Protein-coding gene on chromosome 15 (80,195,481 to 80,252,234, reverse strand). Ensembl gene ENSG00000259417.
Subcellular location: Membrane
Gene Ontology:
Cellular component: membrane
Homologues: Orthologues: chimpanzee CTXND1 (100% identical), dog CTXND1 (100% identical), mouse Ctxnd1 (100% identical), rat Ctxnd1 (100% identical), guinea pig CTXND1 (98% identical), pig CTXND1 (98% identical), rabbit CTXND1 (97% identical), tropical clawed frog ctxnd1 (54% identical).
Diseases named in the same sentence as CTXND1 in open-access papers:
CTXND1 is named in the same sentence as 7 diseases in open-access papers, as found by Europe PMC text mining. Sharing a sentence is not in itself a finding about the gene and the disease.
CTXND1 shares sentences with these, for which no sentence is quoted: tumor (2 papers); cholangiocarcinoma (1); esophageal carcinoma (1); hepatoblastoma (1); paraganglioma (1); pheochromocytoma (1); thyroid carcinoma (1).